AQP4 (aquaporin 4)
Diseases named in the same sentence as AQP4 in open-access papers (continued):
Sharing a sentence is not in itself a finding about the gene and the disease.
cryptococcosis (1 paper, 2024). An acute or chronic, localized or disseminated infection by Cryptococcus neoformans. "Notably, one control from Uganda exhibited AQP4‐IBI values obtained from serum of 2.25 and from DBS of 1.29, the final diagnosis was cryptococcosis." (PMID 39406378, 2024).
cysticercosis (1 paper, 2023). "India ink staining, Cysticercosis antibody, the MycoDot test, the FTA-ABS test, aquaporin-4 (AQP4-IgG), myelin oligodendrocyte glycoprotein (MOG) antibody and myelin basic protein (MBP) antibody in the CSF were negative." (PMID 37248444, 2023).
dependence (1 paper, 2015). "Recent studies have shown that AQP4-deficient mice have attenuated morphine tolerance, inhibited development of morphine physical dependence and impaired morphine analgesia." (PMID 26489685, 2015).
diffuse Lewy body disease (1 paper, 2010). "Furthermore, Rodriguez and colleagues analyzed AQP1 and AQP4 expression in the cerebral cortex of CJD patients compared to that in cases with AD and diffuse Lewy body disease (DLB)." (PMID 21119882, 2010).
distal myopathy (1 paper, 2012). Distal myopathy refers to a group of muscle diseases which share the clinical pattern of predominant weakness and atrophy beginning in the feet and/or hands. "Here, we studied the expression of aquaporin-4 in muscle fibers of a patient with distal myopathy with rimmed vacuoles/hereditary inclusion body myopathy." (PMID 22540328, 2012). "To date, the role of aquaporin-4 water channel in distal myopathy with rimmed vacuoles/hereditary inclusion body myopathy has not been studied." (PMID 22540328, 2012). "Aquaporin-4 might be crucial in determining the survival or degeneration of fast-twitch type 2 fibers in distal myopathy with rimmed vacuoles/hereditary inclusion body myopathy." (PMID 22540328, 2012).
Down syndrome (1 paper, 2025). "Impaired Aβ clearance in AD is linked to changes in AQP4 distribution; however, the role of AQP4 in AD associated with Down Syndrome (DS) is poorly understood." (PMID 40987419, 2025).
end-stage renal disease (1 paper, 2021). "Dysregulation of intrarenal AQP-4 is involved in end-stage renal disease in HIV patients with glomerulosclerosis and renal tubular dysfunction." (PMID 33663503, 2021).
endolymphatic hydrops (1 paper, 2015). An accumulation of endolymph in the inner ear (labyrinth) leading to buildup of pressure and distortion of intralabyrinthine structures, such as cochlea and semicircular canals. "Therefore, failure in the human cochlear AQP4/AQP5–water shunt could contribute to impaired endolymph volume homeostasis, e.g., leading to the endolymphatic hydrops in Ménière’s disease." (PMID 26208470, 2015).
endometrioid ovarian cancer (1 paper, 2018). "However, overexpression of AQP4 mRNA for endometrioid ovarian cancer was not correlated with OS, HR = 1171517663.86 (0–inf), P=0.097." (PMID 29472315, 2018).
enteritis (1 paper, 2016). Inflammation of the small intestine. "On the other hand, the downregulated expression of several AQPs (AQP1, AQP3, AQP4, AQP7, AQP8, AQP10 and AQP11) in the small and large intestines has been observed in the process of either enteritis or diarrhea." (PMID 27589719, 2016).
erectile dysfunction (1 paper, 2019). Persistent or recurrent inability to achieve or to maintain an erection during sexual activity. "In the recovery analysis, erectile dysfunction occurred more commonly in patients with MOG-Ab disease than in those with AQP4-Ab disease (9 men [41%] vs 1 man [8%]; P = .52)." (PMID 31596489, 2019). "Among men, erectile dysfunction more commonly occurred in patients with MOG-Ab disease than those with AQP4-Ab disease (6 patients [46%] vs 2 patients [29%]; P < .001)." (PMID 31596489, 2019).
esophageal cancer (1 paper, 2021). A primary or metastatic malignant neoplasm involving the esophagus. "Survival univariate/multivariate COX analysis revealed that five genes, ZBTB16, AQP4, ADCYAP1R1, PDGFD, and VIPR2, and two microRNAs, miR-99a-5p, and miR-508-5p, were related to esophageal cancer prognosis." (PMID 34329340, 2021).
esophagus tumors (1 paper, 2021). "Results indicated that patients with highest alteration frequency of AQP4 were those with esophagus tumors of the “amplification” and “deep deletion” subtypes (∼3% frequency)." (PMID 34113257, 2021).
Esotropia (1 paper, 2026). A form of strabismus with one or both eyes turned inward ('crossed') to a relatively severe degree, usually defined as 10 diopters or more. "This group included six cases of NMOSD with AQP4-Abs positivity, one case of MS, 21 cases of functional headache, four cases of psychological disorders, one case of metabolic disease, and one case of esotropia." (PMID 41515652, 2026).
follicular adenomas (1 paper, 2012). "The positive frequency of AQP4 was 100% in follicular adenomas, 90% in follicular carcinomas, and 85% in papillary carcinomas." (PMID 22808259, 2012). "AQP4 was demonstrated in 100% of follicular adenomas, 90% of follicular carcinomas, and 85% of papillary carcinomas, while it was negative in all medullary carcinomas and undifferentiated carcinomas." (PMID 22808259, 2012). "In contrast, we frequently observed AQP4 in the cells of follicular adenomas (100% of cases), follicular carcinomas (90% of cases), and papillary carcinomas (85% of cases)." (PMID 22808259, 2012). "We identified AQP4 mRNA expression in follicular adenomas and papillary carcinomas but not in undifferentiated carcinomas or medullary carcinomas." (PMID 22808259, 2012).
fragile X-associated tremor/ataxia syndrome (1 paper, 2022). Fragile X-associated tremor/ataxia syndrome (FXTAS) is a rare neurodegenerative disorder characterized by adult-onset progressive intention tremor and gait ataxia. "Despite the relationship between glymphatic dysfunction and neurodegenerative diseases, dysfunction of glymphatic system has not yet been studied in Fragile X-associated tremor/ataxia syndrome (FXTAS) and its association with AQP4 genetic variants is unknown." (PMID 36688175, 2022).
gastric adenocarcinoma (1 paper, 2020). "In a human gastric adenocarcinoma cell line transfected with rat M1 AQP4, the endosomal route was found to be linked to AQP4 redistribution, because AQP4 was identified in late endosomes, from where it is assumed to recycle back to the plasma membrane after histamine washout." (PMID 32192013, 2020).
Granuloma (1 paper, 2015). A compact, organized collection of mature mononuclear phagocytes, which may be but is not necessarily accompanied by accessory features such as necrosis. "Results showed that the granulomas developed after the deposition of parasite eggs in both AQP4 KO and WT mice livers." (PMID 25604731, 2015).
Graves disease (1 paper, 2012). Graves' disease is an autoimmune disorder that leads to overactivity of the thyroid gland (hyperthyroidism).It is caused by an abnormal immune system response that causes the thyroid gland to produce too much thyroid hormones. "In hyperplastic thyroid tissues such as thyroids with Graves’ disease or multinodular goiters, our immunohistochemical analyses revealed the AQP4 protein in most of the tissues: a positive frequency of 92% in Graves’ disease thyroids and 97% in multinodular goiters." (PMID 22808259, 2012).
hearing loss (1 paper, 2024). "Some mild functional impairments (e.g., alterations in retinal response to light and hearing loss) were observed in AQP4 KO mice, which we have not checked for our AQP4 KO rats in this study." (PMID 39543281, 2024).
HIV-associated neurocognitive disorder (1 paper, 2020). HIV-associated neurocognitive disorder (HAND) remains a common complication of HIV infection in the combination antiretroviral therapy (ART) era. "Up to 30% of people with HIV (PWH) suffer from HIV-associated neurocognitive disorders (HAND), and changes in AQP4 may be clinically important as a contributor to cognitive disturbances." (PMID 33134185, 2020).
hydronephrosis (1 paper, 2022). Collection of urine in the renal pelvis that results in dilatation of the renal pelvis and calyces. "In particular, a previous study showed of decreased kidney AQP4 expression in mice with hydronephrosis." (PMID 36003297, 2022).
Hypercholesterolemia (1 paper, 2017). An increased concentration of cholesterol in the blood. "Whereas AQP4 deletion mice show increased levels of Aβ accumulated in the brain, it is likely that AQP4 also takes part in the Aβ transport and maintaining the redox homeostasis in the glial cells of mice with hypercholesterolemia." (PMID 28432486, 2017).
Hyperinsulinemia (1 paper, 2021). An increased concentration of insulin in the blood. "We aimed to determine the risk association of hyperinsulinemia in NMOSD patients with seropositive AQP4-IgG and the serum levels of interleukin (IL)-6 and IL-17A compared with the control group." (PMID 33879088, 2021).
hypertrophic cardiomyopathies (1 paper, 2022). "Recent breakthroughs indicate that inhibition of hydrogen peroxide permeation through AQP1 provides a new approach to treat hypertrophic cardiomyopathies, and inhibition of AQP4 localization with the licensed drug trifluoperazine provides compelling evidence for a new approach to treating CNS edema." (PMID 35898407, 2022).
internuclear ophthalmoplegia (1 paper, 2017). "The clinical presentation of brainstem involvement was different between the two groups, where the AQP4-positive patients presented with persistent vomiting or hiccups as opposed to internuclear ophthalmoplegia in the seronegative group." (PMID 28203460, 2017).
iron overload (1 paper, 2024). "But the role of AQP4 in posthemorrhagic hydrocephalus development and the association between AQP4 and iron overload are not clear." (PMID 37208490, 2024).
leukodystrophy (1 paper, 2021). Leukodystrophies are a group of rare, progressive, metabolic, genetic diseases that affect the brain, spinal cord and often the peripheral nerves. "AQP4 redistribution is also observed leukodystrophies caused by adult-onset small vessels diseases other than CARASAL, including CADASIL and CARASIL." (PMID 34082828, 2021). "Expression of selective neurovascular unit markers such as claudin-5, zona occludens 1, laminin, PDGFRβ, aquaporin-4 and α-dystroglycan was investigated in eight different leukodystrophies using immunohistochemistry." (PMID 34082828, 2021). "We chose one or more leukodystrophy patient representative of each disease category, and investigated expression of claudin-5, ZO-1, laminin, PDGFRβ, α-dystroglycan and AQP4 together with UEA I and/or GFAP." (PMID 34082828, 2021). "Redistribution of AQP4 in AxD, ALSP, PMD, LARS2-related leukodystrophy, X-ALD and CARASAL strongly points towards an astrocytic dysfunction." (PMID 34082828, 2021).
lipid metabolic disorders (1 paper, 2023). "Additionally, mice given HFD showed a considerable downregulation of the AQP-4 gene in the kidney, which Kuhns and Pluznick (2018) hypothesized that it was caused by an increase in cellular ROS generation resulting from lipid metabolic disorders, similarly to AQP-3 expression." (PMID 38357327, 2023).
lymph node metastases (1 paper, 2022). "Moreover, a low AQP4 membrane expression was positively correlated with a more advanced disease status, e.g., lymph node metastases (p = 0.046)." (PMID 36233821, 2022).
malaria (1 paper, 2011). Malaria is a serious and sometimes fatal disease caused by a parasite that commonly infects a certain type of mosquito which feeds on humans. "Variable levels of AQP4 immunolabelling were observed in the brainstem of individual cases with severe malaria although highest levels were associated with the subpial regions." (PMID 21923924, 2011). "One possible scenario in severe malaria is that AQP4 does not prevent opening of the BBB or vasogenic oedema formation but, rather, promotes water clearance from the brain, limiting the development of cytotoxic oedema." (PMID 21923924, 2011). "Strong AQP4 staining could be found in a punctate fashion in a peri- or paravascular location on astrocyte foot processes and perivascular glial cells around vessels of all calibre, with and without sequestered malaria parasites." (PMID 21923924, 2011).
medullary carcinomas (1 paper, 2012). "Reverse transcriptase polymerase chain reaction (RT-PCR) analyses revealed AQP3 mRNA expression only in medullary carcinomas and AQP4 mRNA expression in follicular cell-derived tumors except for undifferentiated carcinomas." (PMID 22808259, 2012). "We did not observe AQP4 in the cells of undifferentiated carcinomas or medullary carcinomas." (PMID 22808259, 2012).
melanoma (1 paper, 2019). A malignant, usually aggressive tumor composed of atypical, neoplastic melanocytes. "Several factors have already been implicated in peritumoral edema in other cancers, such as vascular endothelial growth factor-A, aquaporin-4, and metalloproteinases, but further study is needed to identify the critical edema mediators in melanoma and to understand how they are affected by CPIs." (PMID 31362777, 2019).
motor neuron disease (1 paper, 2020). "Of those, one opted out and two were excluded after subsequent diagnoses of anti‐AQP4‐positive NMO and motor neuron disease, respectively." (PMID 32253768, 2020).
multinodular goiter (1 paper, 2012). Nodular goiter characterized by more than one discrete tissue mass. "Hyperplastic follicular cells in most of the Graves’ disease thyroids and multinodular goiters were positive for AQP4 in their cytoplasmic membranes; the positive frequency was 92% in Graves’ disease thyroids and 97% in multinodular goiters." (PMID 22808259, 2012).
multiple system atrophy (1 paper, 2022). Multiple system atrophy (MSA) is a neurodegenerative disorder characterized by autonomic failure (cardiovascular and/or urinary), parkinsonism, cerebellar impairment and corticospinal signs with a median survival of 6-9 years. "Whereas in the atypical PD, multiple system atrophy, reduced perivascular AQP4 expression was associated with alpha-synuclein deposits and astrocyte activation." (PMID 36361716, 2022).
Nephropathy (1 paper, 2025). A nonspecific term referring to disease or damage of the kidneys. "Despite the high expression of AQP4 in renal tissue, there is no clear evidence that AQP4-IgG drives primary glomerular disease, and in this case the nephropathy was clinically stable." (PMID 41562061, 2025).
Organizing pneumonia (1 paper, 2025). "Organizing pneumonia might represent a systemic manifestation of NMOSD secondary AQP4-ab targeting pulmonary tissue." (PMID 40729219, 2025).
osteoporosis (1 paper, 2015). A condition of reduced bone mass, with decreased cortical thickness and a decrease in the number and size of the trabeculae of cancellous bone (but normal chemical composition), resulting in increased fracture incidence. "Furthermore, the management of AQP4-seropositive LONMOSD is complicated by more common occurrence of DM and osteoporosis in these patients, limiting the use of corticosteroid treatment." (PMID 26337073, 2015).
otorrhea (1 paper, 2022). "However, AQP4 and -6 mRNA expression levels were significantly decreased in patients with COM accompanied by otorrhea compared with COM patients without otorrhea." (PMID 35216465, 2022).
ovarian carcinoma (1 paper, 2018). A malignant neoplasm originating from the surface ovarian epithelium. "Based on previous evidences as well as our results, we can acknowledge that AQP0, AQP1, and AQP4 high mRNA expression were significantly associated with poor prognosis in ovarian cancer patients." (PMID 29472315, 2018). "Increased expression of AQP4 mRNA was significantly correlated with poor OS for all ovarian cancer, HR = 1.54 (1.2–1.97), P=0.00062 and serous ovarian cancer, HR = 1.55 (1.17–2.05), P=0.0022." (PMID 29472315, 2018). "Whereas AQP1 (stages I + II and III + IV), AQP4 (stages I + II and III + IV), and AQP5 (stage I + II) expressions revealed remarkably unfavorable OS in all ovarian cancer patients." (PMID 29472315, 2018). "Our results revealed that higher AQP0, AQP1, and AQP4 mRNA expression were correlated with poor OS, whereas higher AQP3, AQP5, AQP6, AQP8, AQP10, and AQP11 showed better OS in ovarian cancer patients." (PMID 29472315, 2018). "On the other hand, mRNA expression of AQP1 (grades I and II), AQP4 (grades I, II, and III), AQP6/2L (grade I), AQP10 (grade II) showed a worse OS in ovarian cancer patients." (PMID 29472315, 2018). "Similarly, high AQP4 level showed markedly unfavorable prognosis both in well and poorly differentiated cancer and early (I + II) and advanced stage (III + IV) ovarian cancer." (PMID 29472315, 2018). "Although study has not mentioned about AQP4 correlation with ovarian cancer, consistent with the previous results, we documented that AQP4 mRNA expression in ovarian cancer was correlated with poor prognosis to OS in all ovarian cancer, especially with the serous ovarian cancer type." (PMID 29472315, 2018).
Pancytopenia (1 paper, 2024). An abnormal reduction in numbers of all blood cell types (red blood cells, white blood cells, and platelets). "This study presents for the first time a case of AQP4-IgG seropositive refractory NMOSD patient combined with SS and pancytopenia with significant response to inebilizumab." (PMID 38899058, 2024). "We presented a case of AQP4-IgG seropositive refractory NMOSD patient combined with SS and pancytopenia with significant response to inebilizumab." (PMID 38899058, 2024). "In March 2023, the patient was admitted to our hospital and was formally diagnosed with AQP4-IgG seropositive NMOSD combined with SS and pancytopenia." (PMID 38899058, 2024). "This case report represents a significant finding that inebilizumab in AQP4-IgG seropositive NMOSD patient not only improves symptoms of NMOSD and reduces disease relapses but also effectively alleviates symptoms of concurrent SS and pancytopenia." (PMID 38899058, 2024).
papilloma (1 paper, 2017). A benign epithelial neoplasm that projects above the surrounding epithelial surface and consists of villous or arborescent outgrowths of fibrovascular stroma. "All five papilloma cases showed focal clusters of tumor cells with increased AQP4 immunoreactivity in both the membrane and cytoplasm, without apparent polarization." (PMID 28184993, 2017).
paraneoplastic neurological syndromes (1 paper, 2022). "Other normal or negative antibody tests included myelin basic protein (MBP), myelin oligodendrocyte glycoprotein (MOG), aquaporin-4 (AQP4), antibodies associated with paraneoplastic neurological syndromes (PNS), and antiganglioside complex antibody profiles." (PMID 35139901, 2022).
paroxysmal Hemicrania (1 paper, 2020). Paroxysmal hemicrania (PH) is a primary headache disorder characterized by multiple attacks of unilateral pain that occur in association with cranial autonomic symptoms. "We are aware of one case report, describing a patient presenting with paroxysmal hemicrania as first symptom of an AQP4-Ab-positive NMOSD." (PMID 33473247, 2020). "As in primary paroxysmal hemicrania, indomethacin has been effective in the case of AQP4-Ab-positive NMOSD-related paroxysmal hemicrania, but evidence is limited." (PMID 33473247, 2020).
pericarditis (1 paper, 2023). An inflammatory process affecting the pericardium. "The number of patients who needed an echocardiographic examination and the prevalence of pericarditis were significantly higher in the AQP4-Ab-positive subgroup than in the AQP4-Ab-negative subgroup (P = 0.013 and 0.018, respectively)." (PMID 37208665, 2023).